PKD1 (polycystin 1, transient receptor potential channel interacting)
Diseases named in the same sentence as PKD1 in open-access papers (continued):
Sharing a sentence is not in itself a finding about the gene and the disease.
prostate carcinoma (continued). "In addition, PKD1 colocalizes with E-cadherin at the cell junctions, and binds to and phosphorylates E-cadherin, thus stabilizing the interaction of E-cadherin with catenins, which induces cell–cell adhesion and reduces prostate cancer cells motility." (PMID 35805075, 2022). "Moreover, PKD1 was found to be severely downregulated following progression from androgen-dependent to androgen-independent prostate cancer, and to affect the motility and invasion of prostate cancer via interaction with E-cadherin." (PMID 30818786, 2019). "Thus, androgen may repress PKD1 through an AR-induced FGFR/FRS2/MEK/ERK pathway to inhibit PKD1 expression in prostate cancer cells." (PMID 28077787, 2017). "Although previous studies have demonstrated that curcumin treatment modulates the levels and transcription activity of AR, the activation of PKD1 by curcumin and the inhibition of β-catenin activity might be another mechanism for the regulation of AR function and prostate cancer growth." (PMID 22523587, 2012). "In order to determine if curcumin can modulate the expression or activity of PKD1, androgen-independent prostate cancer C4-2 cells were treated with curcumin for varying time points, and the expression of total PKD1 and active PKD1 was determined using PKD1 and phospho PKD1 antibody antibodies." (PMID 22523587, 2012). "Thus natural compounds that modulate PKD1 activation might help in prevention and treatment of prostate cancer." (PMID 22523587, 2012). "Therefore, non-toxic, natural compounds that upregulate the expression or activity of PKD1 may help in the prevention and or treatment of prostate cancer." (PMID 22523587, 2012). "Therefore, molecules that modulate PKD1 expression or activity may play an important role in the prevention and or treatment of prostate cancer." (PMID 22523587, 2012). "PKD1 and PKD2 play anti-apoptotic and pro-survival roles in response to the apoptotic agent PMA, a phorbol ester, in LNCaP prostate cancer cells." (PMID 35805075, 2022). "A recent study has revealed the ability of curcumin to activate protein kinase D1 (PKD1), leading to attenuation of the oncogenic signaling by β-catenin and MAPK and consequent inhibition of prostate cancer." (PMID 30818786, 2019). "In androgen-sensitive prostate cancer cells, depletion of FRS2 blocked R1881-induced PKD1 suppression at both the transcriptional and protein levels." (PMID 28077787, 2017). "In the androgen-independent prostate cancer cell line DU145, silencing of PKD1 induces the expression of mesenchymal markers like vimentin and N-cadherin." (PMID 26848698, 2016). "SD-208 inhibited the growth of PC3 prostate cancer cells with an IC50 of 17μM, and its anti-proliferative activity was reversed by overexpression of PKD1 and PKD3, indicating inhibition of PKD accounts for the anti-proliferative effect of SD-208." (PMID 25747583, 2015). "Additionally, the activation of PKD1 using natural compounds like curcumin or Bryostatin-1, in concurrence with the observed tumor suppressor function for PKD1, also leads to decreased nuclear β-catenin functions and lower cell proliferation in prostate cancer cells." (PMID 25149539, 2014). "In this study, we have demonstrated that curcumin activates PKD1, attenuates β-catenin/TCF transcriptional activity and enriches membrane β-catenin resulting in the suppression of prostate cancer growth." (PMID 22523587, 2012). "Curcumin mediated PKD1 activation suppressed nuclear β-catenin/TCF transcription activity and inhibited the growth of prostate cancer in cell line and xenograft animal model." (PMID 22523587, 2012). "To determine if the compounds were active PKD1 inhibitors in cells, we determined their ability to inhibit phorbol 12-myristate 13-acetate (PMA)-induced activation of PKD1 in LNCaP prostate cancer cells." (PMID 23028574, 2012). "When tested in prostate cancer cells, all compounds inhibited PMA-induced autophosphorylation of PKD1, with kb-NB142-70 being most active." (PMID 20444281, 2010).
prostate carcinoma (continued). "Three novel chemotypes inhibited phorbol ester-induced endogenous PKD1 activation (i.e., PKD Ser916 phosphorylation) in LNCaP prostate cancer cells and were structurally dissimilar to CID 755673, BKPDi and CRT5, revealing an expanded diversity of PKD1 small molecule inhibitors." (PMID 21998636, 2011). "The authors also demonstrated that PKD1 interacts with β3 integrin to activate ERK signaling, which leads to increased secretion of matrix metalloproteinase (MMP)-2 and MMP-9, therefore suppressing prostate cancer cell proliferation as well as colony formation." (PMID 33807058, 2021). "However, the in vivo tumor-suppressive function of PKD1 in prostate cancer, particularly in the PTEN/PKD1 double-knockout mice, has not been reported." (PMID 33807058, 2021). "Similarly, the Balaji group reported that PKD1 expression was reduced in metastatic prostate cancer samples but not in benign and primary tumor samples." (PMID 33807058, 2021). "In addition, PKD isoforms directly activate the NF-κB pathway: In HeLa cells, PKD1 activates NF-κB via oxidative stress signaling, while PKD2 supports the pIKKβ degradation pathway, and PKD3 is responsible for p65 phosphorylation of NF-κB in prostate cancer cells." (PMID 29258556, 2017).
liver cysts (21 papers, 2012 to 2026). "Mice with homozygous Pkhd1 mutations have kidney and liver cysts that were aggravated by reduced Pkd1 dosage." (PMID 41300696, 2025). "The causative genes of severe liver cysts were five variants in PKD1, one variant in GANAB, and one variant in PKHD1." (PMID 36833371, 2023). "This implies that, even though the dysfunction of these enzymes impacts the glycosylation of a wide variety of proteins, the kidney and liver cysts in these individuals emerge and develop through a similar molecular mechanism as PKD1-caused ADPKD with PLD." (PMID 37628703, 2023). "Furthermore, in this study, ADPKD patients with Pkd1 nonsense mutation located closer to the 5ʹ end of Pkd1 gene were more likely to have a maximum diameter index value of hepatic cyst ≥ 6 cm." (PMID 38671465, 2024). "A novel pathogenic variant c.8005delG was also identified in PKD1 in a 41-years old individual with urolithiasis, HTN, and liver cyst phenotype." (PMID 37543885, 2022). "Among 42 patients with bilateral PKD caused by PKD1 and/or PKD2 mutations, 11 (26.2%) had combined hepatic cysts or polycystic liver." (PMID 31056860, 2019). "Since 85% of ADPKD patients between 25 and 34 years of age develop liver cysts, we assessed liver cyst formation in Pkd1 cKO mice." (PMID 27356569, 2016). "An adult male with multiple renal and hepatic cysts harbored a similar complex deletion involving PKD1 (MIM: 601313; Family 11), while another participant recruited due to intellectual disability and short stature (Family 14) carried a similar de novo rearrangement involving KMT2B (MIM: 606834)." (PMID 38776926, 2024). "In ADPKD, while PKD1 and PKD2 mutations are known to cause both kidney and liver cysts, the presence of liver cysts without kidney involvement may indicate other genetic causes." (PMID 41411243, 2025).
ciliopathy (20 papers, 2015 to 2025). A genetic disorder of the cellular cilia or the cilia anchoring structures, the basal bodies, or of ciliary function. "Autosomal-dominant polycystic kidney disease (ADPKD) is a ciliopathy characterized by mutations in PKD1 or PKD2, which drive cystogenesis in renal epithelial cells." (PMID 40814262, 2025). "Autosomal-dominant polycystic kidney disease (ADPKD) is a ciliopathy caused predominantly by mutations in the PKD1 or PKD2 gene, encoding for polycystin 1 (PC1) and PC2, respectively." (PMID 40814262, 2025). "Variants in PKD1 and PKD2 comprised 85.3% of the positive findings in this group, and other ciliopathy-associated genes (ALG9, PRKCSH, OFD1) accounted for an additional 3%." (PMID 37794564, 2023). "LA has been found highly abundant in the cell culture medium of another model of ciliopathy, namely, Pkd1-mutant cells, due to enhanced anerobic glycolysis." (PMID 36012682, 2022). "It is plausible that the therapeutic outcome of intervening with PD-1|PD-L1 signaling may differ when using other models of PKD such as germline Pkd2 or ciliopathy models, as well as inducible kidney-specific Pkd1 or Pkd2 knockout models." (PMID 37345660, 2023). "Our demonstration that SKP2 levels were also increased in Pkd1-null kidneys points to the wider applicability of our findings in other forms of ciliopathy-related kidney cyst disease, as opposed to being viewed as a select consequence of the jck mutation." (PMID 36326820, 2022). "In addition to this, 661W cells express several syndromic ciliopathy disease genes which are not expressed at all in hTERT-RPE1 cells, including B9d1, B9d2, Evc2, Pkd1, and Tmem138." (PMID 31024622, 2019). "We have previously demonstrated the feasibility and efficiency of a capture-based NGS multi-gene panel approach (besides PKD1) in a number of other studies for PKD and other ciliopathies, which is not surprising as there are only very few complex or duplicated sites in those other genes discussed." (PMID 25646624, 2015).
pancreatic cancer (19 papers, 2014 to 2025). "Strikingly, in pancreatic cancer cells, loss of PKD1 enhanced secretion of EVs that promoted metastasis of xenograft and pancreatic tumors to lung in mice, demonstrating a role for PKD in aberrant EV secretion." (PMID 37293129, 2023). "The association of PKD1-induced mTOR pathway can be used as a therapeutic strategy for the development of new drugs to target pancreatic cancer." (PMID 31819177, 2020). "This study demonstrates the role of PKD1 in enhancing glucose metabolism of pancreatic cancer cells and defines the underlying molecular mechanisms." (PMID 31819177, 2020). "Our objective was to understand the underlying molecular mechanisms involved in PKD1-induced aberrant glucose metabolism and enhanced aggressiveness of pancreatic cancer." (PMID 31819177, 2020). "Furthermore, PKD1 has been found to exert pro-migratory and -invasive role in many cell types such as intestinal epithelial cells, fibroblasts and pancreatic cancer cells, and to be implicated in several pathways mediating cell migration and invasion." (PMID 25287328, 2014). "Our findings align well with previous literature, where effects of commercially available statins were shown to increase the expression of PKD1 in pancreatic cancer cell line MiaPaCa-255." (PMID 41094040, 2025). "In pancreatic cancer, however, PKD1 appears to be the dominant isoform in highly invasive cell lines and tumor samples." (PMID 37293129, 2023). "Liou GY and collaborators show that PKD1 contributes to very early events in pancreatic cancer development." (PMID 35805075, 2022). "The Storz group generated a conditional PKD1 knockout mouse model to study the role of PKD in the initiation of pancreatic cancer." (PMID 33807058, 2021). "For example, it was reported that PKD1 was highly expressed in skin and pancreatic cancers where it acted as a tumor-promoting factor." (PMID 34858418, 2021). "Although PKD1 being upregulated in acinar cells is known to regulate the duct formation leading to pancreatic cancer initiation and growth, only little is known of how the PKD1 regulates cancer development." (PMID 31819177, 2020). "These interesting findings strongly indicate that PKD1 can be explored as a novel therapeutic target and as a biomarker, inhibition of which can reduce pancreatic cancer progression and metastasis." (PMID 31819177, 2020). "PKD1 expression was predominantly expressed all over the malignant area of the pancreatic cancer tissues when compared with respect to grade, PanIN lesions and overall comparisons." (PMID 31819177, 2020). "The expression profile of PKD1 in human pancreatic cancer tissues and normal samples (N = 45) was investigated by using immunostaining of PKD1 by immunohistochemistry." (PMID 31819177, 2020). "These outcomes indicate that expression of PKD1 in pancreatic cancer cells results in chemo-resistance, which attributes to the deregulated glucose metabolism, and its suppression sensitises gemcitabine in pancreatic cancer cells." (PMID 31819177, 2020). "Except HPAF-II and BxPC3, which showed less expression of PKD1, most pancreatic cancer cells had high expression of PKD1 at both mRNA (PCR) and protein levels (immunoblotting and confocal immunofluorescence)." (PMID 31819177, 2020). "Herein, we report the significance of PKD1 expression in glucose metabolism resulting in pancreatic cancer (PanCa) progression and chemo-resistance." (PMID 31819177, 2020). "Our results suggest a novel role of PKD1 contributing to aberrant glucose metabolism in pancreatic cancer cells, which accelerates PanCa tumorigenesis and chemo-resistance." (PMID 31819177, 2020). "Briefly, our study prospects PKD1 as a novel molecular target in pancreatic cancer for therapeutic intervention." (PMID 31819177, 2020).
pancreatic cancer (continued). "In conclusion, the inhibition of PKD1 by using pharmacological agents and small-interfering RNA/microRNA-mediated techniques can selectively suppress pancreatic tumour growth and metastasis via inhibition of glycolytic influx in PDAC cells." (PMID 31819177, 2020). "The activation of PKD1 promotes pancreatic cancer cell proliferation and increased PKD1 expression contributes to therapy resistance." (PMID 30419840, 2018). "On the other hand, several studies in pancreatic cancer and basal cell carcinoma have demonstrated an opposite role of PKD1 in cancer." (PMID 30419840, 2018). "Meanwhile, overexpression of PKD1 significantly promoted DNA synthesis, anchorage-dependent/−independent growth, tumor cell invasion, and angiogenesis in pancreatic cancer cells." (PMID 30419840, 2018). "Another role for PKD1 during initiation of pancreatic cancer is the activation of Notch signaling downstream of mutant KRas." (PMID 28361035, 2017). "In this mini-review, we highlight the mechanisms of how PKD1 is activated in response to oxidative stress, so far known downstream effectors, as well as the importance of PKD1-initiated signaling for development and progression of pancreatic cancer." (PMID 28361035, 2017). "PKD1 has been shown to increase cell proliferation in breast, prostate, salivary tumors and pancreatic cancers." (PMID 27042159, 2016). "Some studies have shown that PKD1 stimulates NFκB, an important transcription factor involved in a variety of cellular mechanisms that plays a role in increasing the proliferation and growth rate of pancreatic cancer." (PMID 35816294, 2022). "Similarly, PKD1 promotes pancreatic cancer tumorigenesis, chemoresistance and progression through reprogramming cancer cell glucose metabolism." (PMID 35805075, 2022). "PKD1 overexpression enhanced cell viability and resistance to gemcitabine through activating glucose transporter 1 and mTORC1 to increase metabolic adaptation in pancreatic cancer cells." (PMID 33807058, 2021). "In addition, this study suggests a novel role of PKD1 in regulating glucose metabolism in pancreatic cancer, which drives pancreatic tumorigenesis, chemo-resistance and progression." (PMID 31819177, 2020). "Moreover, as suggested by our results, PKD1 has a role in chemo-resistance owing to dysregulated glucose metabolism in pancreatic cancer." (PMID 31819177, 2020). "Since PKD1 links to most transcription factors crucial for the acinar cell de-differentiation process, this kinase may be a critical and targetable component to develop strategies to prevent the development of pancreatic cancer." (PMID 35052641, 2022). "In addition, this study determines an important role of PKD1 in pancreatic cancer chemo-resistance." (PMID 31819177, 2020). "Reactive oxygen species–PKD1 signaling has emerged to be important in the pathophysiology of neurodegenerative diseases, cardioprotection against ischemia/reperfusion injury, tissue inflammation, and several cancers, including basal cell carcinoma and pancreatic cancer." (PMID 28361035, 2017). "The prediction model based on MCOLN1, PKD1, TRPC3, and TPRC7 can also predict the prognosis of pancreatic cancer." (PMID 35898870, 2022). "We also investigated the expression level of PKD1 in a normal pancreatic epithelial cell line (HPNE) and six pancreatic cancer cells, which includes HPAF-II, Panc-1, Capan-1, MiaPaca, AsPC1 and BxPC3 cells." (PMID 31819177, 2020). "Overexpressing PKD1 in pancreatic cancer cells significantly increased their secretion of the proangiogenic factors VEGF and CXC chemokines, and thereby promoted anchorage-independent growth, invasion, and angiogenesis in human pancreatic cancer." (PMID 33807058, 2021).
pancreatic cancer (continued). "ROS-activated PKD1 stimulates transcription factors NF-κB1 and NF-κB2, which up-regulate the expression of EGFR and its ligands TGFα and EGF, thus inducing EGFR/KrasWT signaling cascade and, consequently, pancreatic cancer proliferation and malignant progression." (PMID 35805075, 2022). "CRT0066101 can inhibit cell proliferation, induce apoptosis, reduce PKD1/2 activity induced by neurotensin, reduce neurotensin-induced PKD-mediated Hsp27 phosphorylation, inhibit NF- κB activation, and block NF-κB-dependent proliferation and survival in pancreatic cancer." (PMID 34249722, 2021).